IFT27 (intraflagellar transport 27)
Description:
Small GTPase-like component of the intraflagellar transport (IFT) complex B that promotes the exit of the BBSome complex from cilia via its interaction with ARL6. Not involved in entry of the BBSome complex into cilium. Prevents aggregation of GTP-free ARL6. Required for hedgehog signaling. Forms a subcomplex within the IFT complex B with IFT25. Its role in intraflagellar transport is mainly seen in tissues rich in ciliated cells such as kidney and testis. Essential for male fertility, spermiogenesis and sperm flagella formation. Plays a role in the early development of the kidney. May be involved in the regulation of ureteric bud initiation (By similarity).
Synonyms: RABL4; RAYL; BBS19; FAP156; CFAP156
Tractability: PROTAC: ubiquitination databases record sites on it; its protein half-life has been measured.
Gene: Protein-coding gene on chromosome 22 (36,758,202 to 36,776,309, reverse strand). Ensembl gene ENSG00000100360.
Subcellular location: Cell projection, cilium; Cytoplasm; Cell projection, cilium, flagellum
Pathways (Reactome):
Organelle biogenesis and maintenance: Intraflagellar transport
Gene Ontology:
Molecular function: protein binding; protein carrier chaperone; GTP binding; GTPase activity
Biological process: intracellular protein transport; intraciliary retrograde transport; intraciliary transport; negative regulation of protein localization to ciliary membrane; cilium assembly; intraciliary anterograde transport; kidney development; smoothened signaling pathway; spermatogenesis; vesicle-mediated transport; keratinocyte development
Cellular component: cilium; intraciliary transport particle A; intraciliary transport particle B; ciliary tip; cytoplasm; Golgi apparatus; Golgi membrane; motile cilium; sperm flagellum; centrosome; nucleus; sperm midpiece; sperm principal piece
Genetic constraint (gnomAD): Loss-of-function variants: 14 observed, 20.3 expected, observed/expected ratio (o/e) 0.69, 90% interval 0.46 to 1.08. The upper end of that interval is the gene's LOEUF score, 1.08, which puts it in group 4 of 6, group 1 being the genes least tolerant of losing a copy. Missense variants: 183 observed, 213.01 expected, observed/expected ratio (o/e) 0.86, 90% interval 0.76 to 0.97. Synonymous variants: 84 observed, 84.8 expected, observed/expected ratio (o/e) 0.99, 90% interval 0.83 to 1.19.
Gene-disease validity (ClinGen):
ClinGen rates the evidence that IFT27 causes each of these diseases.
ciliopathy (autosomal recessive): Definitive. A genetic disorder of the cellular cilia or the cilia anchoring structures, the basal bodies, or of ciliary function.
Homologues: Orthologues: chimpanzee IFT27 (100% identical), macaque IFT27 (93% identical), dog IFT27 (92% identical), mouse Ift27 (83% identical), rat Ift27 (81% identical), pig IFT27 (80% identical), guinea pig IFT27 (62% identical), tropical clawed frog ift27 (62% identical), zebrafish ift27 (54% identical). Paralogues in human: RAB2B (36% identical), RAB35 (36% identical), RAB26 (35% identical), RAB37 (34% identical), RAB10 (34% identical), RAB11A (33% identical), RAB30 (33% identical), RAB11B (33% identical), RAB17 (33% identical), RAB2A (33% identical), RAB5A (33% identical), RAB6B (33% identical), and 56 more.
Diseases named in the same sentence as IFT27 in open-access papers:
IFT27 is named in the same sentence as 21 diseases in open-access papers, as found by Europe PMC text mining. Sharing a sentence is not in itself a finding about the gene and the disease. The quoted sentences say what the papers report.
Bardet-Biedl syndrome (8 papers, 2015 to 2025). A ciliopathy with multisystem involvement. "While pathogenic variants in USH1C and IFT27 are associated with autosomal recessive Usher syndrome type 1C and Bardet–Biedl syndrome 19, respectively, mutated ADGRA3 is linked to autosomal recessive RP." (PMID 39766861, 2024). "The final BBS-associated gene discussed that causes Bardet–Biedl syndrome is IFT27 (also known as BBS19)." (PMID 36830640, 2023). "The other was a novel and likely pathogenic variant found in IFT27 (NM_006860.4:c.350G>A; p.Gly117Asp), associated with Bardet-Biedl Syndrome 19 (OMIM #615996)." (PMID 35886058, 2022). "Cells depleted of these proteins due to an IFT27 mutation accumulate abnormal collections of IFT complex B proteins and cause phenotypic Bardet–Biedl syndrome." (PMID 36830640, 2023). "In Bardet–Biedl syndrome, TTC8, BBS9, WDPCP, and IFT27 were shared by the two pipelines, and BBS4, BBS7, BBS12, and IFT74 suffered significantly different selective pressures between TG and BG birds." (PMID 35456484, 2022).
ciliopathy (5 papers, 2014 to 2025). "An animal model zebrafish embryo was co-injected with morpholino oligonucleotides (MO), an expression blocker of ift27, and displayed severe renal anomalies and venter body curvature (ciliopathy) due to loss of function and reduction of ift27 expression." (PMID 37239474, 2023). "In addition, mutations in IFT27 cause BBS, displaying a broad spectrum of ciliopathy phenotypes, including the cardinal retinal degeneration phenotype observed in RAB28 patients." (PMID 27930654, 2016).
Obesity (3 papers, 2018 to 2025). Accumulation of substantial excess body fat. "We report a family with typical BBS features (retinitis pigmentosa, postaxial polydactyly, obesity, cognitive impairment, and atrioventricular septal defect) mutated in IFT27/BBS19." (PMID 30761183, 2019). "Initially the first identified mutations in IFT27 were reported in a consanguineous BBS family presenting with RP, obesity, polydactyly of all extremities, mild intellectual disability, renal failure and hypogenitalism." (PMID 30761183, 2019).
infertile (1 paper, 2025). "We reported that disruption of Ift20, Ift25, and Ift27 in male germ cells resulted in infertility." (PMID 40348912, 2025). "Likewise, IFT81 male mice were infertile associated with reduced IFT-B components in testes, and others, including IFT20, IFT25, IFT27, IFT57, IFT74, and IFT88, but there was no change in the IFT-A complex protein IFT140." (PMID 40348912, 2025).
male infertility (1 paper, 2023). The inability of the male to effect fertilization of an ovum after a specified period of unprotected intercourse. "Mutations in other IFT-B gene additional to IFT74 (IFT81, IFT20, IFT27, IFT172), and in IFT-A genes (IFT140) can cause spermatogenesis defects and male infertility in mice." (PMID 37555648, 2023).
IFT27 also shares sentences with these, for which no sentence is quoted: cone-rod dystrophy (2 papers); atrioventricular septal defect (1); Cognitive impairment (1); developmental delay (1); genetic disease (1); Intellectual disability (1); Jeune asphyxiating thoracic dystrophy (1); Mainzer-Saldino syndrome (1); orofaciodigital syndrome (1); renal agenesis (1); renal failure (1); renal hypoplasia (1); retinal degeneration (1); retinitis pigmentosa (1); Senior-Loken syndrome (1); short rib-polydactyly syndrome (1).